MTTP (microsomal triglyceride transfer protein)
Diseases named in the same sentence as MTTP in open-access papers (continued):
Sharing a sentence is not in itself a finding about the gene and the disease.
non-alcoholic fatty liver disease (5 papers, 2015 to 2023). "More recently, human fetal hepatocyte organoids were used for modeling free fatty acid loading, interindividual genetic variability (PNPLA3 I148M), monogenic lipid disorders (APOB and MTTP mutations), and induced non-alcoholic fatty liver disease (NAFLD)." (PMID 37146581, 2023). "Mutations in the MTTP gene have also been shown to play a role in the development of nonalcoholic fatty liver disease." (PMID 36026493, 2022). "We supposed the regulation of serum lipids and risk of non-alcoholic fatty liver disease (NAFLD) formation may be modified by individual susceptibility related to the MTTP polymorphisms." (PMID 26458397, 2015). "A rare genetic variant in the gene MTTP has been identified as responsible for the development of severe non-alcoholic fatty liver disease in a four-generation family with no typical disease risk factors." (PMID 37484212, 2023).
Cirrhosis (3 papers, 2015 to 2024). A chronic disorder of the liver in which liver tissue becomes scarred and is partially replaced by regenerative nodules and fibrotic tissue resulting in loss of liver function. "A recently identified MTTP rs745447480 variant, which encodes microsomal triglyceride transfer protein (MTP), causes progressive MASLD with subsequent cirrhosis and HCC in homozygotes." (PMID 38921460, 2024). "Here we have clinically characterised a large four-generation family found to have a rare MTTP variant located at the interface with PDI resulting in progressive NAFLD, with consequent cirrhosis, liver failure, and HCC in homozygotes." (PMID 37484212, 2023).
atherosclerosis (2 papers, 2020 to 2022). A disease characterized by the build-up of fatty material and calcium deposition in the arterial wall resulting in partial or complete occlusion of the arterial lumen. "Notebly, implitapide (a molecule containing α-carboline moiety, 6) has reached clinical trails as an microsomal triglyceride transfer protein (MTP) inhibitor to reduce the progression of atherosclerosis." (PMID 36092663, 2022). "Implitapide, a microsomal triglyceride transfer protein (MTP) inhibitor, had been shown to reduce progression of atherosclerosis." (PMID 36092663, 2022). "miR-30c was also suggested to participate in improvement of atherosclerosis and hyperlipidemia via decreasing lipid biosynthesis and secretion of lipoproteins by downregulating lysophosphatidylglycerol acyltransferase 1 (LPGAT1) and microsomal triglyceride transfer protein (MTP)." (PMID 32962281, 2020).
colitis (2 papers, 2013 to 2022). Inflammation of the colon. "Intestine-specific knockout of murine MTTP rather increased the tumor burden in a colitis-associated carcinogenesis model." (PMID 35831271, 2022). "Here we studied the severity of experimental colitis and the development of colitis associated cancer (CAC) in mice with an inducible block in chylomicron secretion and fat malabsorption, following intestine-specific deletion of microsomal triglyceride transfer protein (Mttp-IKO)." (PMID 23805328, 2013).
Glucose intolerance (2 papers, 2020 to 2024). Glucose intolerance (GI) can be defined as dysglycemia that comprises both prediabetes and diabetes. "Furthermore, the results of HOMA-IR, ITT, and GTT assays demonstrated that the beneficial effect of hepatocyte ChREBP deficiency on IR and glucose intolerance was blocked by hepatic MTTP overexpression." (PMID 38532128, 2024).
Hypocholesterolemia (2 papers, 2016 to 2022). An decreased concentration of cholesterol in the blood. "Chylomicron and VLDL synthesis are both severely compromised in two recessive disorders causing severe hypocholesterolemia: chylomicron retention disease, which is caused by Sar1b deficiency, and abetaliproteinemia, which is due to deficiency of MTTP." (PMID 27013658, 2016). "For the cases with hypocholesterolemia phenotype, we studied five genes (APOB, PCSK9, MTTP, SAR1B, and ANGPTL3)." (PMID 37138899, 2022).
liver disease (2 papers, 2015 to 2021). "Of the novel ALT‐ and AST‐associated variants, a missense variant in the gene MTTP has the most significant association with liver disease traits albeit suggestively significant (rs3816873, p.I128T, OR = 0.921, p = 3.33 × 10−5)." (PMID 34184762, 2021). "Collectively these results suggest that rs3816873 potentially modifies MTTP function and support its modulation to modify liver disease risk." (PMID 34184762, 2021). "Among the novel liver enzyme associations, a missense variant (rs3816873, p.I128T, pALT = 4.15 × 10−15, pAST = 3.16 × 10−12) in the gene microsomal triglyceride transfer protein (MTTP) has the most significant association with liver disease traits (NASH NAFLD composite, OR = 0.921, p = 3.33 × 10−5)." (PMID 34184762, 2021). "The deleterious effect on liver damage of the impaired ability to secrete triglycerides in VLDL is also supported by the association between progressive liver disease and rare apolipoprotein B (APOB) and microsomal triglyceride transfer protein (MTTP) mutations directly causing VLDL retention." (PMID 26273621, 2015).
alcoholic fatty liver disease (1 paper, 2022). Lipid infiltration of the hepatic parenchymal cells that is due to alcohol abuse. "As the near downstream gene of C4orf17, MTTP has been suggested to be related to alcoholic fatty liver disease, possibly because alcohol exposure could increase triglyceride and cholesterol levels." (PMID 35864541, 2022).
alcoholic liver diseases (1 paper, 2022). A disorder caused by damage to the liver parenchyma due to alcohol consumption. "To further investigate the role of miR-141/200c in vivo in regulating TG secretion in alcoholic liver disease, we examined protein levels of HNF1B, MTTP, and APOO in WT- and KO-mice–fed CB or EB." (PMID 35460694, 2022).
co-infection (1 paper, 2014). "maxima co-infection compared with uninfected controls (ANXA1, HSP90B1, VEGFA, MTTP, TNFSF11B, TCF12, APP, and CXCL14)." (PMID 25504150, 2014).
hypothyroidism (1 paper, 2025). Abnormally low levels of thyroid hormone. "The effects of hypothyroidism (treatment factor) were significant for the content of MTTP, CD36, PEPT1, and GLUT2 proteins, while the interaction between time and treatment was significant only for L-FABP content." (PMID 39958687, 2025). "The hypothyroidism disrupts L-FABP, CD36, PEPT1, and GLUT2 circadian rhythms, reduces the MTTP amplitude, and punctually decreases the FATP4 content at the moment of the light to dark photoperiod transition." (PMID 39958687, 2025). "In addition, the hypothyroidism reduced L-FABP content at ZTs 16 and 20, FATP4 at ZT12, MTTP at ZT20, PEPT1 at ZT 8 (while P = 0.09 was depicted at ZT4), and GLUT2 at ZT16 according to the pairwise comparisons." (PMID 39958687, 2025).
liver cancer (1 paper, 2023). An epithelial or non-epithelial malignant neoplasm that arises from the liver. "In this study, we first found that curcumin induced changes in the expression of CYP1A1, HMGCS2, HMOX1, LCN2, and MTTP, which are enriched in metal ion homeostasis, in all three liver cancer cell lines." (PMID 36838613, 2023).
metabolic syndrome X (1 paper, 2022). "For example, in the subnetwork for metabolic syndrome X, pathogenesis genes AGTR2 and ADRA1A are at the top hierarchical layer for chemokine signaling, while IRF1, MXZB1, MTTP, and CNTC are at the top layer in cytokine signaling." (PMID 35404985, 2022).
tumor (9 papers, 2018 to 2025). "MTTP levels were significantly correlated with three scores (immune, stromal, and extimate) and immune checkpoints in at least half of tumor types." (PMID 40213543, 2025). "High expression of MTTP is correlated with the infiltration of diverse immune cells and regulates ferroptosis in GC cells, providing a potential target for tumor immunotherapy." (PMID 40213543, 2025). "Immunohistochemical staining showed relatively expression of GPX4, xCT, MTTP and ki67 in tumor tissues from ob/ob mice than in those from C57 mice, and these changes were inhibited by treatment with L‐OHP and recovered by injecting adipocyte exosomes." (PMID 35978266, 2022). "Immunohistochemical staining showed relative expression of GPX4, xCT, MTTP and ki67 in tumor tissues from ob/ob mice." (PMID 35978266, 2022). "Since our multi-omics analysis showed that lipid metabolism plays an important role in tumor progression, we focused further on the analysis of Lomitapide, an inhibitor of microsomal triglyceride-transfer protein (MTTP), which could inhibit tumor growth in all LEGOs." (PMID 38273014, 2024). "Changes in the protein content in transplanted tumor tissues were detected, and the expression of GPX4, xCT and MTTP was decreased in the KD‐MTTP group." (PMID 35978266, 2022).
cancer (5 papers, 2014 to 2025). A tumor composed of atypical neoplastic, often pleomorphic cells that invade other tissues. "Adipose-derived exosomes can promote chemoresistance to oxaliplatin via transpotting exosomal microsomal triglyceride transfer protein (MTTP) into cancer cells and thus regulating PRAP1/ZNFE1/GPX4 signal pathway." (PMID 38737906, 2024). "Therefore, we suggest that the anticancer effects of lomitapide in cancer cells strongly implicate its engagement of mTOR and not MTTP." (PMID 35831271, 2022).
metabolic disorder (4 papers, 2011 to 2023). "In this work we characterize two other unrelated patients affected by this metabolic disorder and we identify a novel mutation in MTTP gene leading to a non functional protein." (PMID 23556456, 2013). "Among rare lipoprotein disorders, microsomal triglyceride transfer protein genocopies the effects on the central nervous system of both genetic- and environment-driven forms of vitamin E deficiency." (PMID 21215387, 2011). "ABL is a rare autosomal recessive metabolic disorder characterized by complete absence of plasma apo B-containing lipoproteins that results from mutations in MTTP gene." (PMID 23556456, 2013).
cardiovascular disease (2 papers, 2013 to 2025). "Therefore, we have tested the hypothesis that the rare allele of the -164T > C polymorphism in MTTP alters the risk of cardiovascular disease (CVD), depending on the cholesterol levels." (PMID 23356586, 2013).
MTTP also shares sentences with these, for which no sentence is quoted: Hypercholesterolemia (8 papers); Ataxia (4); infection (3); type 2 diabetes mellitus (3); chronic hepatitis C (2); chylomicron retention disease (2); folate deficiency (2); gastric cancer (2); glioma (2); retinitis pigmentosa (2); acanthocytosis (1); alcohol (1); anemia (1); Arthritis (1); astrocytoma (1); autosomal recessive disease (1); cardiac disease (1); chronic hepatitis (1); colon cancer (1); coronary artery disease (1); cryptogenic cirrhosis (1); deafness (1); dilated cardiomyopathy (1); Failure to thrive (1); gastrointestinal disease (1); genetic disorders (1); genotype (1); glioblastoma (1); hepatitis C (1); hyperparathyroidism (1).
A further 16 diseases each share a sentence with MTTP in 1 paper.